PON1 (paraoxonase 1)
Diseases named in the same sentence as PON1 in open-access papers (continued):
Sharing a sentence is not in itself a finding about the gene and the disease.
dyslipidemia (continued). "It was also observed that decreased PON1 activity was related to the increased occurrence of atherogenic dyslipidemia." (PMID 35888704, 2022). "At present, by implementing therapeutic lifestyle changes (aerobic exercises) and niacin, at least in men with metabolic syndrome, we can increase PON1 activity and PON1 concentration." (PMID 33762698, 2021). "Obese patients with evidence of small nerve fibre damage, compared to those without, had significantly higher serum triglycerides, lower PON-1 activity and a higher prevalence of metabolic syndrome." (PMID 34131170, 2021). "In the current study, we first describe a marked dyslipidemia involving abnormalities in hepatic lipid metabolism, suppression of circulating PON1 activity and high BLM in the K/BxN mouse model of RA." (PMID 33033318, 2020). "We then demonstrate that overexpression of the human PON1 transgene (Tg) improves the dyslipidemia in arthritic mice, preventing increases in BLM with arthritis induction and decreasing arthritis activity and damage." (PMID 33033318, 2020). "This was the first randomized clinical trial to compare the effects of drinking yerba mate and green tea on serum levels of PON-1 and leptin in individuals affected by overweight or obesity and dyslipidemia." (PMID 30660196, 2019). "In summary, this study indicates that the DNA methylation level of CpG4 in the PON1 promoter would lead to a low expression of PON1 mRNA and potentially induce the occurrence of clopidogrel resistance in patients with dyslipidemia." (PMID 30891852, 2019). "In patients suffering from T2DM and dyslipidemia, 12-weeks treatment with rosuvastatin was reported to increase serum PON-1 activity and to lower plasma ADMA concentration." (PMID 29301528, 2018). "In the present study, we found that there is a significant reduction in the PON1 arylesterase and lactonase activity in children and adolescents with metabolic syndrome." (PMID 29732027, 2018). "From the ROC curve, it is clear that PON1 activities are better predictors of metabolic syndrome in children and adolescents than lipid profile or HDL levels." (PMID 29732027, 2018). "For example in metabolic syndrome the finding of unmodified PON1 protein concentration and decrease in PON1 activity supports that PON1 is inactivated by oxidized lipids." (PMID 24666514, 2014). "This research group found that ciprofibrate administration increased HDL-cholesterol concentration and serum PON1 activity in patients with metabolic syndrome." (PMID 22315585, 2012). "In rats receiving a fructose-enriched diet (an experimental model of liver steatosis and metabolic syndrome), bezafibrate reduced oxidative stress and increased serum PON1 levels." (PMID 22315585, 2012). "Paraoxonase 1 imbalance plays a relevant role in the pathogenesis of dyslipidemia." (PMID 40362292, 2025). "The combined therapy decreased the dyslipidemia and increased the PON-1 activity." (PMID 38892513, 2024). "It is worth noting that in PCOS females, diminished PON1 activity is connected to dyslipidemia, elevated circulating testosterone, insulin resistance, endothelial dysfunction, inflammation, and oxidative stress, all of which are significant factors that contribute to cardiovascular disease." (PMID 38982395, 2024). "This could be the reason for the higher PON-1 values found in RBCs lysates in this study since hypothyroidism induces dyslipidemia leading to the mobilization of LDLs." (PMID 38662314, 2024). "MPO is a protein that is usually present in healthy people’s plasma in very low concentrations, and levels are elevated in atherosclerotic diseases like acute coronary syndrome or those with metabolic syndrome, and it affects PON1 activity, decreasing its activity." (PMID 38474211, 2024).
dyslipidemia (continued). "PCOS can be associated with PON1 deficiency; however, mostly depending on the polymorphism, in Kashmiri women only, 108C/T, but not 55L/M genes, were associated with PCOS, increasing the chance of developing metabolic syndrome and insulin resistance." (PMID 38474211, 2024). "In conclusion, lycopene may enhance PON1 expression by inhibiting PON1 gene methylation in subjects with metabolic syndrome." (PMID 35889799, 2022). "Additionally, the reduction in PON1 activity with increase in the severity of metabolic abnormalities is a likely consequence of oxidative stress in metabolic syndrome, exceeding the antioxidant capacity of the enzyme." (PMID 35453382, 2022). "Furthermore, lycopene supplementation was shown to restore PON1 activity in cases of hyperlipidemia, diabetes, obesity, and metabolic syndrome." (PMID 35889799, 2022). "Of particular interest, another study observed that caloric restriction (1,200 kcal/day) for 3 months, combined with physical activity in obese patients with metabolic syndrome led to a surprising decrease of PON1 protein concentration, but increased PON1 activity after weight loss." (PMID 34881279, 2021). "In addition, CCQS-specific and QSBS-specific genes were also enriched in metabolic Syndrome and cerebrovascular disease, respectively, in which Syndrome-specific DPs involved in the diseases were PON1 and ADIPOQ for CCQS, APOE and APOA1 for QSBS." (PMID 34702323, 2021). "However, in the subgroup with dyslipidemia, we discovered that PON1 mRNA expression was reduced in CR patients." (PMID 30891852, 2019). "Hence, we turned our focus to DNA methylation, and our present study found that in the group of CR patients with dyslipidemia, CpG4 of PON1 hypermethylation and expression of PON1 mRNA were lower." (PMID 30891852, 2019). "Numerous studies have shown a reduction in paraoxonase 1 activity in people with metabolic syndrome.At present, more and more factors are being discussed that predispose early to the onset of atherosclerotic lesions and, consequently, to cardiovascular diseases." (PMID 31737129, 2019). "In the subgroup with dyslipidemia, we discovered that higher CpG4 levels of the PON1 promoter indicated a poorer clopidogrel response (cases versus controls (%): 51.500 ± 14.742 vs 43.308 ± 10.891, P = 0.036), and the PON1 mRNA expression was reduced in CR patients." (PMID 30891852, 2019). "Thus, the aim of the present study was to estimate PON1 arylesterase (ARE), lactonase (LACT) activity in patients with metabolic syndrome and to compare PON1 activities in children and adolescents with metabolic syndrome and the controls." (PMID 29732027, 2018). "The altered PON1 arylesterase and lactonase activities in metabolic syndrome could have two possible explanations." (PMID 29732027, 2018). "In individuals with obesity and dyslipidemia, the increase in Ox-LDL levels can be attributed to a reduction in the antioxidant defense mechanisms, primarily due to the decreased activity of enzymes like superoxide dismutase (SOD) and paraoxonase-1 (PON-1) associated with HDL." (PMID 40699839, 2025). "Consequently, PON1 may offer protection against conditions like diabetes, metabolic syndrome, cardiovascular disease, and PCOS that have decreased insulin levels." (PMID 38982395, 2024). "Moreover, the latest research shows that the amount of paraoxonase-1 in patients with diabetes and metabolic syndrome may be reduced, which would correlate with its deficit in patients with endometrial cancer." (PMID 36290747, 2022). "Therefore, in the beginning stages of metabolic syndrome, hyperglycemia could be defined as reduced paraoxonase 1 activity and corresponding increases in enzymatic antioxidants, which generally mitigate relative elevations in ROS and lipid peroxidation." (PMID 33401717, 2021).
dyslipidemia (continued). "In short, our findings show that a combined curcumin-aminoguanidine therapy prevent dyslipidemia, increase PON 1 activity, and normalize NOx levels in DM; this may constitute a potentially effective new strategy for the management of cardiovascular complications observed in DM." (PMID 32566072, 2020). "They suggested HDL-associated PON1 activity may be involved at least partially in the eNOS-derived NO production, as the activity of PON1 increased in both serum and HDL3 fractions from metabolic syndrome patients after 10 weeks of training." (PMID 31817387, 2019). "Paraoxonase-1 (PON-1) is a pleiotropic enzyme associated with high-density lipoprotein (HDL) that contributes to the systemic protection against toxic agents deriving from oxidative stress (OxS), exacerbating inflammatory response, dyslipidemia, and pollution exposure." (PMID 29317982, 2017). "This study aims to investigate the relationship between tetranectin (TETRA) and paraoxonase 1 (PON1) levels and the severity of heart failure in patients with hypertension and dyslipidemia." (PMID 40422267, 2025). "This study aimed to investigate the relationship between tetranectin (TETRA) and paraoxonase 1 (PON1) levels and the severity of heart failure in patients with hypertension and dyslipidemia." (PMID 40422267, 2025). "Additionally, alterations in circulating PON1 levels and activity have been reported in several diseases involving oxidative stress and inflammation, including cardiovascular diseases, chronic renal failure, Alzheimer’s disease, metabolic syndrome, and chronic liver impairment." (PMID 35453382, 2022). "In metabolic disorders, the presence of several factors that are linked to abnormally high glucose levels, such as hyperinsulinemia, dyslipidemia, and oxidative stress, lead to a decrease of PON1 activity, especially due to glycation of HDL-PON1." (PMID 31430977, 2019). "Reduced PON1 activity may also compromise HDL function, exacerbating dyslipidemia and vascular inflammation." (PMID 40868959, 2025). "Based on data, PON-1 can transfer to the membrane, can be involved in HDL-mediated cholesterol outflow, and participate in the pathogenesis of oxidative stress-related diseases (including cardiovascular syndrome, HIV, metabolic syndrome)." (PMID 37511134, 2023). "The elevation of HDL-c and PON-1, an enzyme that protects LDL from lipid peroxidation, was found after egg ingestions; therefore, individuals with metabolic syndrome who had consumed eggs presented a decrease in C-reactive protein levels, insulin levels, and insulin resistance, compared to baseline." (PMID 36313094, 2022). "Obese participants with small nerve fibre damage had higher serum triglycerides (P = 0.02), lower PON-1 activity (P = 0.002) and higher prevalence of metabolic syndrome (58% vs. 23%, P = 0.02) compared to those without." (PMID 34131170, 2021). "The patients with metabolic syndrome showed a significantly lower level of PON1 (arylesterase) activity (mean 111 AU) than those without metabolic syndrome (mean 133 AU)." (PMID 24228251, 2013). "Dyslipidemia may affect HDL-dependent antioxidant enzymes, including PON1." (PMID 38982880, 2024). "Furthermore, obese subjects with small nerve fibre damage, compared to those without, had higher serum triglycerides and prevalence of metabolic syndrome and lower PON1 activity." (PMID 34131170, 2021). "The reductions in the activities of PON1 found in the present study and their relationship to HDL-cholesterol suggest that the decrease of these serum enzymes may participate in the pathogenesis of metabolic syndrome." (PMID 29732027, 2018). "The PON1 rs854560 allele T was associated with dyslipidemia (p = 0.014) and increased risk of ischemic cerebral stroke (OR 1.38, 1.02–1.85, p = 0.034), while the PON1 rs705379 TT variant was associated with CVD mortality (HR 1.27, 95% CI 1.03–1.57, p = 0.025), while PON1 rs662 was not." (PMID 37175471, 2023).
Obesity (77 papers, 2009 to 2026). Accumulation of substantial excess body fat. "Although these factors are associated with PON1, further research is needed to evaluate their potential role as risk indicators for obesity." (PMID 41897374, 2026). "The PPI network analysis revealed 24 PON1 protein interactors associated with obesity and oxidative stress." (PMID 39857440, 2025). "Mexican studies have revealed that the LM/MM and QQ genotypes of PON1 polymorphisms are linked to decreased PON1 activity and obesity risk." (PMID 40428368, 2025). "A total of 24 common protein interactors associated with PON1, obesity, and oxidative stress were identified." (PMID 39857440, 2025). "Gene-based association analysis identified associations between rare and very rare PON1 variants and obesity across all but one test, indicating a robust association in our cohort." (PMID 39334710, 2024). "Overall, these results strengthen the genetic association between PON1 and obesity by extending previous findings from common SNPs to include rare variants." (PMID 39334710, 2024). "For PON1 specifically, there have, however, been reports showing an association between PON1 SNPs and obesity." (PMID 39334710, 2024). "There are gender-related differences in factors independently associated with decreases in PON1, as obesity and obesity-related oxidative stress are more important in females, whereas inflammation is more significant in males." (PMID 36675097, 2023). "There is a discrepancy in the scientific literature regarding the changes in PON1-related variables associated with obesity." (PMID 38136158, 2023). "Numerous studies reported lower paraoxonase 1 activity in patients with obesity or past myocardial infarction, suggesting that the low activity of PON1 serves as a CVD risk factor." (PMID 35888704, 2022). "None of these studies have combined these different elements to examine complex obesity phenotypes in relation to PON1 polymorphisms, DNA methylation status and associated changes in gene expression and enzymatic activity." (PMID 34389043, 2021). "Future longitudinal studies on large obesity cohorts will be necessary to shed light on the causality of the association observed between PON1 status and hepatometabolic disease." (PMID 34389043, 2021). "In sedentary children and adolescents with obesity, we found that decreased PON1 activities were associated with hyperinsulinemia and insulin resistance, as well as higher triglycerides and lower HDL-cholesterol concentrations." (PMID 34356595, 2021). "A targeted multi-omics approach was applied to examine the role of PON1 in relation to obesity-associated fatty liver disease." (PMID 34389043, 2021). "Genetic studies in patients with obesity further indicate a possible correlation of the disease occurrence with PON1 polymorphisms." (PMID 34389043, 2021). "There was a significant decrease in the serum paraoxonase-1 levels in individuals with obesity-associated hyperleptinemia and compared to those participants with a normal weight (3.44 ± 1.08 ng/mL vs. 9.57 ± 2.89 ng/mL, p < 0.001)." (PMID 34829950, 2021). "The aim of this study was therefore to determine the different regulatory aspects of PON1 variability and to examine them in relation to the predisposition to obesity-associated fatty liver disease." (PMID 34389043, 2021). "Other studies have also associated reduced PON1 expression with adverse lipid metabolism and recognized this as a risk factor for obesity, liver steatosis and its more severe subtype steatohepatitis." (PMID 34389043, 2021). "This latter explanation is most consistent with our results and best reflects the general idea that an increase in PON1 exhibits a protective role against the susceptibility for obesity and associated fatty liver disease." (PMID 34389043, 2021). "Low levels of PON1 activity have been observed in association with obesity, a major risk factor for cardiovascular disease (CVD)." (PMID 31390816, 2019).
Obesity (continued). "It is currently believed that low PON1 activity is a risk factor for cardiovascular complications in people with obesity." (PMID 31737129, 2019). "In this scenario, the biological mechanisms underlying the decreased activity of PON1 in obesity and obesity-related pathological conditions still need to be fully clarified." (PMID 31390816, 2019). "Along these lines, one would expect that the association of obesity with both genetic factors (e.g. PON1 genotype and genetic ancestry) would be more prominent at age 2 compared to age 5, as we observed in our cohort." (PMID 23658746, 2013). "We observed a significant association of child PON1192 genotype and PON1 status with both BMI Z-score and obesity status at age two." (PMID 23658746, 2013). "Since PON1 allele frequencies are quite different by ethnic groups and prevalence of obesity clearly varies between ethnic and racial groups as well, it is important to consider this critical factor." (PMID 23658746, 2013). "Since PON1 polymorphisms and obesity both vary between ethnic groups, we estimated proportional genetic ancestry using 106 ancestral informative markers (AIMs)." (PMID 23658746, 2013). "As their results imply, integrating proteomic and imaging data improved early detection of NAFLD and suggested that PON1 may serve as both a biomarker and therapeutic target in obesity-associated liver disease." (PMID 41374408, 2025). "Additionally, analysis of rare variants reveals an association with obesity for PON1 and MASLD-related liver fibrosis for PON2." (PMID 39334710, 2024). "Declines in PON1 activity were independently associated with elevated CRP in boys with obesity." (PMID 37372026, 2023). "In another study, an association between methylation at two PON1 promoter CpG sites with body weight and waist circumference was reported, which proves that PON1 DNA methylation may influence obesity risk." (PMID 35889799, 2022). "The authors concluded that lower PON-1 activity could contribute to the greater risk of cardiovascular disease associated with obesity." (PMID 36463116, 2022). "Another drawback is the cross-sectional nature of our study, as it does not allow us to determine whether the relationship we found between high PON1 activity and hepatic manifestations was a cause or a consequence of obesity and/or NAFLD." (PMID 34389043, 2021). "Variability within the different PON1 -omics levels was explored in a hepatometabolic patient cohort (HEPADIP cohort) to identify clinicopathological associations of PON1 regulation with predisposition to obesity-associated fatty liver disease." (PMID 34389043, 2021). "Serum paraoxonase-1 (PON1) encoded by PON1 as an enzyme associated with HDL-C could be a protector against oxidative damage in obesity." (PMID 24621099, 2014). "To determine whether confounding by population stratification significantly affects the relationship between PON1 and obesity we looked at their associations while adjusting for proportional ancestry." (PMID 23658746, 2013). "Since obesity is a complex trait, the reduced power of adjusting for multiple testing can mask associations with some polymorphisms, such as paraoxonase 1 (PON1), which may also contribute to obesity heritability with small but significant effects." (PMID 23658746, 2013). "Despite the small sample size, our study found indications of a gene-environment interaction between prenatal pesticide exposure and the PON1 Q192R genotype that might affect the risk of obesity and related diseases later in life." (PMID 22615820, 2012). "Additionally, rare PON1 variants were strongly associated with obesity." (PMID 39334710, 2024). "Our study further substantiates the relevance of PON1 in obesity and various MASLD-related liver features, by extending previous findings from common SNPs to include rare variants." (PMID 39334710, 2024).